CCND1 (cyclin D1)
Diseases named in the same sentence as CCND1 in open-access papers (continued):
Sharing a sentence is not in itself a finding about the gene and the disease.
cancer (continued). "More specifically, these studies show that CD36 can promote the activation of the MAPK signaling pathway, upregulate protein expression of Bcl2 and cyclin D1 and engage with the TGF-β signaling for epithelial to mesenchymal transition (EMT) by cancer cells." (PMID 34215227, 2021). "As previously quoted, palpociclib induces autophagy in cancer, targeting CDK4 and CDK6, via the LKB1 and Ser325 phosphorylation resulting in a CCND1-mediated, reduced activation of AMPK." (PMID 34445095, 2021). "Cyclin D1 (CCND1) was demonstrated to induce post-DNA damage cell cycle arrest and apoptosis in different types of cancers." (PMID 33898418, 2021). "Metformin seems to be involved in cancer cell inhibition through AMPK and cyclin D1 downregulation leading to cell cycle arrest and apoptotic pathways activation." (PMID 33350292, 2021). "Some other investigations have manifested the anti-cancer effect of Res against OCa through AMPK activation, downregulation of the protein cyclin D1, EMT inhibition." (PMID 34959716, 2021). "This suggests that the cancer cell activity was reduced, and the p-ERK1/2 and cyclin D1/CDK4/6 axis was involved in the development of CRC." (PMID 34434893, 2021). "We found that high CCNP expression correlated with a high expression of Axin2 (p < 0.0001), cyclin D1 (CCND1) (p = 0.0026), Lgr5 (p < 0.0001) and Ascl2 (p < 0.0001), suggesting that CCNP and stemness are broadly intertwined in human cancer." (PMID 34604945, 2021). "Matrine arrests the cell cycle and induces apoptosis in several cancer cell lines, and the mechanism is downregulated cell cycle-related proteins CDK1, Cyclin B1 and Cyclin D1." (PMID 34809653, 2021). "We used western blotting to investigate the expression of several factors that are known to play significant roles in human cancers, including CDK6, Cyclin D1, PIK3CA, P-AKT, and P-mTOR." (PMID 34966665, 2021). "Cluster 7 included cells with aberrant neuronal identity that expressed neuronal development genes (NEFM, DCX, STMN2, HES6) but also cell cycle and cancer-related genes (CRABP2, CCND1, MYC)." (PMID 33771987, 2021). "Overexpressed cyclin D1 (CCND1) can hyperactivate cyclin-dependent kinase 4 and 6 (CDK4/6) and induce cisplatin resistance in HNSC, TGCT and other cancers." (PMID 33995018, 2021). "Copy number amplification events in CCND1, CCND3, CDK6, ERBB2, FGFR1, MET, and PIK3CA also showed higher expression compared to wild types across various cancer types." (PMID 34429404, 2021). "When GSK3β is inhibited by AKT, free β-catenin accumulate and translocate to the nucleus, ultimately activating downstream target genes such as cyclin D1, C-Myc, CD44, FN1, C-JUN, Slug, L1CAM, and MMP14; thus contributing to tumorigenesis and EMT of cancer." (PMID 34546849, 2021). "And studies have shown that SAHA generally fights against cancer by upregulating the p21 (CDKN1A) cancer suppressor gene, PTEN, p27 and decreasing levels of pro-growth genes CDK2, CDK4, cyclin D1 and cyclin E." (PMID 32682428, 2020). "Clustering analysis of the frequency of events targeting CDK4, CCND1, CDKN2A, and RB1 indicates analyzed human cancers fall into five distinct groups separated largely by RB1 status and the co-occurrence of CCND1, CDK4, and CDKN2A." (PMID 32242058, 2020). "Tamoxifen is the golden therapy for hormonal BC, but resistance of cancer cells to tamoxifen contributes to the recurrence of BC due to many reasons, including high levels of AIB1 and cyclin D1." (PMID 33050377, 2020). "To investigate signaling pathways activated for CCND1 amplification tumors, we performed GSEA comparing the CCND1 amplification group and the CCND1 neutral group in the TCGA pan-cancer cohort." (PMID 32903763, 2020). "Prior studies that have noted the importance of CCND1 and FGFR dysfunction in the initiation of cancers." (PMID 32380883, 2020). "Cancer stem cell markers ALDH1A2, ALDH7A1, CD44, and CCND1 were also upregulated in CTCs compared to HDs." (PMID 32998338, 2020).
cancer (continued). "Nevertheless, controversy regarding overexpression of Cyclin D1 protein and/or CCDN1 gene amplification in relation to survival of cancer patients still exists." (PMID 33317149, 2020). "Thus, the combined treatment of a drug leading to a depletion of cyclin D1 and a DNA damage inducer, such as irradiation, could be an interesting potential therapy to target cancers with a high rate of DNA repair, especially in the case of chemo- and radio-resistant tumors." (PMID 32992652, 2020). "Abnormalities in expression and amplification of some important CCP-related genes or regulators such as cyclin D1, E1, and E2F1 were frequently observed in various cancer types." (PMID 32370292, 2020). "This binding resulted in the expression of several target genes involved in angiogenesis, proliferation, migration and invasion of cancer cells, such as VEGFA, EGFR, c-Myc, Cyclin D1 and MET." (PMID 33088626, 2020). "A molecular analysis of cell cycle markers such as p21, p27, cyclin D1, and CDK4 also provided strong proof of cell cycle arrest, which leads to apoptosis induction in cancer cells." (PMID 31979292, 2020). "Cyclin D1 and COX-2 are overexpressed in a variety of cancers and mediate cancer cell proliferation." (PMID 33233701, 2020). "Initiation of canonical Wnt signaling triggers transcription of several effector genes important for tumorigenesis and cancer progression, including c-MYC and cyclin D1." (PMID 33007980, 2020). "Examples included CCND1 and EGFR, i.e. key regulators of cell cycle progression and PI3K-AKT signaling in a variety of normal and cancer tissues." (PMID 32412911, 2020). "Cyclin D1 is induced by Raf/MAPK/ERK cascade and plays a key role during proliferation in various cancers." (PMID 32923479, 2020). "A number of target genes, including Bcl-2, Bcl-xL, Slug, Snail, survivin and cyclin D1, which have STAT3 binding sites in their promoters, regulate chemoresistance and radioresistance in a variety of cancer cells." (PMID 32872659, 2020). "The inhibition of cyclin D1 and CDK4/6 has been considered a promising strategy for the treatment of cancers including TNBC." (PMID 32508655, 2020). "The oncogenic roles of the CCND1 have been demonstrated in various studies, with numerous human cancers including thyroid breast, LADC, liver, colon, and prostate, overexpress CCND1." (PMID 32380883, 2020). "Recently, studies showed that AMPK activation induced G0/G1 phase arrest by decreasing expression of cyclin D1 and CDK4 in diverse cancer cells." (PMID 31887988, 2019). "TTP also regulates the expression of cancer-related proteins (Fos, Myc, COX-2, cIAP2, E2F1, Bcl-2, Mcl-1, LATS2, Lin28, and Cyclin D1), which contribute to inflammation, apoptosis, and angiogenesis in CRC." (PMID 31440515, 2019). "For example, oncogenes including MYC, KRAS, and CCND1 showed strong CES with increasing copy numbers, corroborating the recent studies about cancer dependency on these gene amplifications." (PMID 31732481, 2019). "Additionally, a previous study focusing on several human cancers including GC reported that the expression of cyclin D1 gene was also notably high in GC, and targeting this gene using specific inhibitory compounds may serve as another effective treatment for GC." (PMID 31007611, 2019). "Surprisingly, only eight identified genes (CCND1, CDK6, CDKN2A, KDM5A, MDM2, MLL3, PPP2R1A, and RB1) are shared by UniCovEx and CovEx, and they are all NCG cancer genes." (PMID 30828525, 2019).
cancer (continued). "To identify the downstream modulator of TARBP2, we determined the expression of several key factors that have been reported to modulate self-renewal and drug resistance of cancer cells, including SOX2, Nanog, OCT4, Lin28A, CCND1." (PMID 30759864, 2019). "ERBB2, CCND1, CCNE1 are well-characterized oncogenes present among our curated set of cancer driver databases." (PMID 31729402, 2019). "Since CCND1 mRNA was negatively correlated with proton RBE in two types of cancer, BC and NSCLC, we chose cyclin D1 as the next target." (PMID 31591311, 2019). "ASF1a interacts with the transcription factor β-catenin and activates the downstream genes cyclin D1, myc, Lgr5, and ZEB1, promoting cancer development and progression." (PMID 30692519, 2019). "Another study demonstrated that miR-520d inhibits c-Myc, Cyclin D1, and MMP9 expression, and their inhibitory role demonstrated the reduction in the proliferation, invasion, and migration of cancer cells." (PMID 31212896, 2019). "EP decreased migratory and invasive effects of cancer cells while inhibiting the expression of total AKT1, AKT2, BCL-XL, Cyclin D1 and c-Myc in the tested IBC cells." (PMID 30837881, 2019). "The overexpression of miR-149 increased the drug sensitivity of cancer cells and inhibited the EMT through the FOXM1/cyclin D1/MMP2 axis." (PMID 31552107, 2019). "To further study its role in liver malignancy, we examined the expression of several cyclin family members in large scale cancer datasets provided by TCGA, including CCNA1, CCND1, and CCNE1." (PMID 31349793, 2019). "Next, we checked the localization of cell cycle regulating proteins such as CHK1, CHK2, Cyclin D1, and CDK6 in Lanatoside C treated cancer cells and observed the presence of proteins in the extracellular matrix." (PMID 31783627, 2019). "Constitutively, the activation of STAT3 is well known to play an essential role in the development of multiple cancers, including OSCC, where its hyper-activation up-regulates the transcription of cyclin D1, survivin, and Bcl-xL." (PMID 31315217, 2019). "In cancer cells, knockdown of PVT1 expression inhibits the expression of cyclin D1 and CDK4, which suggests that PVT1 positively regulates the expression of cyclin D1 and CDK4." (PMID 31309249, 2019). "Myricetin inhibits cell proliferation, tumor metastasis, angiogenesis, and induces cell death by inhibiting cancer signaling pathways such as MAPK, AP-1/cyclin D1, JAK-dependent STAT3 in various cancer cell lines." (PMID 31100782, 2019). "There were several established cancer genes involved in a total of 12 common CNAs identified according to GISTIC, including EGFR, CCND1, FHIT, and FAT1." (PMID 31159251, 2019). "Therefore, cyclin D1 may become a new target for the clinical treatment of cancer." (PMID 31583003, 2019). "In agreement with our data, low-density lipoprotein receptor-related protein-1 (LRP-1) and ApoE-binding receptors promote cancer cell migration via induction of MMP-2 and MMP-9 expression, and are involved in inducing cyclin D1 in interstitial fibroblasts." (PMID 31275318, 2019). "Cyclin D1 (CCND1) is a core cell cycle regulator and is frequently overexpressed in human cancers, often via amplification, translocation or post-transcription regulation." (PMID 29969496, 2018). "On the other hand, both qPCR and western blot assays confirmed that NKILA suppressed activation of several NF-κB target genes including CCND1, TWIST1, MMP9 and XIAP, all of which play vital roles in cancer growth and metastasis." (PMID 29348395, 2018).
cancer (continued). "Recent studies regarding cell apoptosis showed the biological correlation between cyclin D1 and SOD1 in various human diseases, including genetic diseases and cancers." (PMID 30279365, 2018). "Fourth, in cancer cells, SIRT1 overexpression induced a G1-phase cell cycle arrest via cyclin D1 signaling, an effect that is in line with our finding on RA-FLS cell cycle arrest." (PMID 29784872, 2018). "RNA-seq found that knockdown of HOXC-AS3 affected key cancer-related genes, such as p21, FAS, and CCND1." (PMID 30286788, 2018). "It is also notable that we identified over 10 cancer-related genes (including PHGDH, CCND1, IGFBP-2, XAGE1B/E, CYP4F22, RBM11, ORAOV1, MDK, UGT3A5, SSX5, FBL, NKX2) potentially overexpressed in EFT tumors." (PMID 30093970, 2018). "The present study demonstrates that ZEB2 induces expression of Sp1-regulated genes such as survivin, bcl-2, cyclin D1, and VEGF by cooperating with Sp1 to promote cancer cell survival and endothelial cell activation directly during metastasis." (PMID 29416649, 2018). "During cancer cell proliferation, AKT phosphorylation can accumulate the cyclin D1 protein and also prevent the release of calcium from the mitochondria and hence avert cell apoptosis." (PMID 30186180, 2018). "Several studies have so far confirmed that SAHA can inhibit the expression of cyclin D1 and activate p21 (WAF1/CIP1) function, resulting in cancer cell cycle arrest and induction of cancer cell death." (PMID 30583560, 2018). "CCND1 amplification and overexpression as well as CDKN2A inactivation are frequent genetic alterations in many cancers, including NPC." (PMID 30236142, 2018). "It has been found that cancer cells harboring aberrant STAT3 activity had elevated levels of anti-apoptotic and cell cycle regulating proteins like cyclin D1 and c-Myc." (PMID 29636641, 2018). "In this study, we found that ZEB2 upregulated survivin, cyclin D1, and vascular endothelial growth factor (VEGF) through cooperation with Sp1 to promote cancer cell survival and proliferation and endothelial cell activation." (PMID 29416649, 2018). "As one of the most important proteins to regulate cell cycle, Cyclin D1 can activate CDK4, which allows the cell cycle to progress through G1 into S, thus promoting the development of various cancers." (PMID 29422775, 2018). "Given the addiction of cancer cells to PCNA and cyclin D1, their targeted inhibition has been shown to successfully suppress cancer growth without affecting normal cells." (PMID 30218018, 2018). "Overexpression of cyclin-dependent kinases (CDKs) and cyclin proteins (CCND1, CCNE1, and CCNB1) are found in many human cancers." (PMID 28466007, 2017). "The identified downstream targets of miR-365 include cell division cycle 25A (CDC25A), cyclin D1 (CCND1), transcription termination factor 1 (TTF1), interleukin 6 (IL-6) and nuclear factor I B (NFIB) in various types of cancers." (PMID 28556798, 2017). "Indeed, subcellular localization of Cyclin D1 outside the nucleus has been reported to correlate with a lower proliferative index in different cancer types, this suggesting that the restriction of Cyclin D1 to the perinuclear region may allow the suppression of G1-S progression." (PMID 28985758, 2017). "The multiple mechanisms involved in cell proliferation (Cyclin D1, c-Myc), cell survival (Bcl-2, Bcl-xL), and apoptosis (caspase -8, 3, and 9) may mediate the permissive chemotherapy and chemopreventive effects for a selective targeting of highly proliferating cancer cells over normal cells." (PMID 29029547, 2017). "For example, for the two miRNA pairs that both are members of the miR-15 family (miR-15a/b), the top three possible co-functional targets for the non-cancer diseases are IFNG, MTHFR, RARB, while for cancers are BCL2, CDKN1A and CCND1." (PMID 28340554, 2017). "Of note, cyclin D1 and fibronectin protein levels were increased according to the range of SF2 in cancer cell lines from NCI-60 (P = 0.0015 and P = 0.0325, respectively)." (PMID 28859688, 2017).
cancer (continued). "In the DEN/PB model and in human cancer cell lines, suppression of vascular endothelial growth factor (VEGF)-A - a regulator of neovascularisation - and of the cell cycle regulator cyclin D1 resulted in protection from HCC development." (PMID 28915576, 2017). "Key molecules, such as cyclin D1 (CCND1) and survivin (BIRC5), whose deregulation is closely related to cancer, were found among the more than 100 targeted genes activated by wnt signalling." (PMID 28926938, 2017). "Immunohistochemistry confirmed a higher expression for cyclin D1 and CDK4 proteins in cancer samples." (PMID 28852180, 2017). "Amazingly, SLC7A11 and cyclin D1 were up-regulated in the cancer tissues at both the mRNA and protein levels, and the same trend was seen in the SLC7A11-AS1low cancer tissues compared to the SLC7A11-AS1high cancer tissues." (PMID 29348845, 2017). "Thus our study revealed the multifaceted regulation of cyclin D1 by sesaminol, the underlying mechanisms of which may be explained by the direct interaction with ANT2, as well as the possibility of sesaminol as a mother compound of anticancer agents for cyclin D1-overexpressing cancers." (PMID 28368390, 2017). "Over-expression of cyclin D1 and EGFR proto-oncogenes has been reported in different types of cancer, and in more recent studies EGFR inhibitors have been used for cancer treatment." (PMID 29354245, 2017). "c-Myc and CCND1 were common to both the HR and ESC-like cancer signature genes and were therefore investigated." (PMID 28246384, 2017). "Other studies confirmed that SAHA inhibited expression of cyclin D1 and activated p21WAF1/CIP1 function, resulting in cancer cell cycle arrest and induction of cancer cell apoptosis." (PMID 27926517, 2017). "Cyclin D1 and CDK4 are key cell cycle proteins, and have been found to be overexpressed in several types of human cancer." (PMID 28591705, 2017). "The role of NFκB signaling in GBM recurrence is consistent with its proposed role in GBM initiating cell (GICs) biology and proliferation, which is thought to be due to NFκB-dependent regulation of cancer stem cell genes, including CD44 and cyclin D1." (PMID 28556811, 2017). "We already know that re-expression of ARHI in cancer cells inhibits signaling through the Ras/MAP pathway, induces p21WAF1/CIP1, and downregulates cyclin D1." (PMID 29156798, 2017). "Overexpression of ARHI in cancer cells inhibits signaling through the Ras/MAP and PI3K-AKT pathways, induces p21WAF1/CIP1, and downregulates cyclin D1." (PMID 29156798, 2017). "Cyclin D1 and CDK4 are important regulatory proteins in cell growth and are overexpressed in many cancer cells." (PMID 27670681, 2016). "Of the top 207 transcripts annotated as ‘cell cycle’ by GO analysis, we focused on nine well-known cell cycle regulators (CCNA2, CCND1, CDK6, CHK1, CHK2, MAPK1, MAP2K1,SKP2, and TFDP1) for further analyses, due to their known functions in cancers." (PMID 26958940, 2016). "AP-1 signaling was reported to regulate cyclin D1, cyclin E and MMP9 in various cancers including NSCLC." (PMID 27184257, 2016). "We noticed several cell cycle related genes such as CDK1 (↑), CCND1 (↑) and SMAD3 (↓), that have been widely investigated in various cancers." (PMID 27602771, 2016). "Little is known about PPIC in cancer, however PPIA and another PPIase PIN1 have been shown to interact with key growth and signalling proteins including cyclin D1, CDK10, cdc27, and PLK1, with diverse downstream effects on MAPK signalling." (PMID 27852308, 2016). "Cyclin D1 is a direct target of the MAPK/ERK signaling pathways, which controls cellular processes such as cell proliferation and migration in cancer development." (PMID 27061029, 2016).